RNU6-720P (RNA, U6 small nuclear 720, pseudogene)
Gene: Small nuclear RNA gene on chromosome 3 (149,917,342 to 149,917,449, reverse strand). Ensembl gene ENSG00000252172.
Homologues: Orthologues: chimpanzee U6 (100% identical), macaque U6 (86% identical). Paralogues in human: RNU6-429P (74% identical), RNU6-903P (74% identical), RNU6-949P (74% identical), RNU6-1024P (73% identical), RNU6-11P (73% identical), RNU6-12P (73% identical), RNU6-13P (73% identical), RNU6-24P (73% identical), RNU6-32P (73% identical), RNU6-33P (73% identical), RNU6-34P (73% identical), RNU6-354P (73% identical), and 1285 more.